PALS2 (protein associated with LIN7 2, MAGUK p55 family member)
Synonyms: VAM-1; MPP6; VAM1; p55T
Tractability: Antibody: UniProt places it where antibodies can reach, with medium confidence; its Gene Ontology location is reachable by antibodies, with medium confidence. PROTAC: ubiquitination databases record sites on it.
Gene: Protein-coding gene on chromosome 7 (24,572,936 to 24,694,193, forward strand). Ensembl gene ENSG00000105926.
Subcellular location: Membrane
Gene Ontology:
Molecular function: protein binding
Biological process: protein-containing complex assembly
Cellular component: extracellular exosome; cell-cell junction; membrane; plasma membrane; organelle
Genetic constraint (gnomAD): Loss-of-function variants: 25 observed, 54.74 expected, observed/expected ratio (o/e) 0.46, 90% interval 0.33 to 0.64. The upper end of that interval is the gene's LOEUF score, 0.64, which puts it in group 2 of 6, group 1 being the genes least tolerant of losing a copy. Missense variants: 496 observed, 602.2 expected, observed/expected ratio (o/e) 0.82, 90% interval 0.76 to 0.89. Synonymous variants: 218 observed, 208.63 expected, observed/expected ratio (o/e) 1.04, 90% interval 0.94 to 1.17.
Homologues: Orthologues: chimpanzee PALS2 (100% identical), macaque PALS2 (100% identical), dog PALS2 (99% identical), guinea pig PALS2 (99% identical), pig PALS2 (99% identical), rabbit PALS2 (99% identical), mouse Pals2 (98% identical), rat Pals2 (97% identical), tropical clawed frog pals2 (87% identical), zebrafish pals2a (76% identical), zebrafish pals2b (75% identical), Drosophila melanogaster vari (43% identical), and 5 more. Paralogues in human: MPP2 (70% identical), CASK (42% identical), MPP7 (38% identical), MPP1 (36% identical), MPP3 (34% identical), PALS1 (33% identical), MPP4 (33% identical).
Diseases named in the same sentence as PALS2 in open-access papers:
PALS2 is named in the same sentence as 2 diseases in open-access papers, as found by Europe PMC text mining. Sharing a sentence is not in itself a finding about the gene and the disease. The quoted sentences say what the papers report.
infection (1 paper, 2021). The state of being infected such as from the introduction of a foreign agent such as serum, vaccine, antigenic substance or organism. "Genome exploration demonstrated that PALS2 possesses many extra functional genes, such as RNAP subunits and an extra lysis protein, which may have strengthened the infection ability of PALS2 and broadened its host spectrum." (PMID 33763042, 2021).
PALS2 also shares sentences with these, for which no sentence is quoted: tumor (1 paper).